AURKB (aurora kinase B)
Diseases named in the same sentence as AURKB in open-access papers (continued):
Sharing a sentence is not in itself a finding about the gene and the disease.
tumor (continued). "Combination targeting of AURKB and orally available BH3 mimetic, ABT-263 led to a decrease in cell viability in several different tumor cell lines compared to monotherapy with VX-680." (PMID 33915740, 2021). "We further discovered the possible role of tumor suppressors DLC1 and HLF in AURKB-mediated adverse outcome of LUAD." (PMID 33612479, 2021). "The levels of USP7 and mitotic markers, including AURKB, CCNB1, and PLK1, were higher in tumor samples than in normal tissues." (PMID 33207738, 2020). "GSK 1070916, a potent inhibitor for AURKB and AURKC, has demonstrated anti-tumor growth capacity in a broad range of tumors." (PMID 33202573, 2020). "In MCF-7 cell lines, combination therapy enhanced the downregulation of essential components of the cell cycle (HMMR, AURKB, BIRC5) that control proliferative activities and tumour growth alongside downregulation of the anti-senescence markers FOXM1 and E2F1." (PMID 32787886, 2020). "We also demonstrated that HI-511, a novel AURKB and BRAF V600E inhibitor, suppresses tumor growth and overcomes vemurafenib resistance in vitro and in vivo." (PMID 32863956, 2020). "In fact, PLK1, CDK1, and AURKB were significantly upregulated in tumor tissues, by contrast, ATM was markedly downregulated expressed in tumor tissues, except CDK2." (PMID 33292231, 2020). "In the favorable ccrcc2_3 subtypes, miR-204-5p was strongly upregulated, predicted long OS, and repressed several targets that are involved in tumor invasiveness and metastasis (MMP3, MMP9, AURKB, FBN2, ITGB4, SPDEF)." (PMID 32915890, 2020). "By searching the public database, we found that AURKB gene was over-expressed in BRCA tumors as well as in the luminal, HER2, and TNBC tumor subtypes." (PMID 31244554, 2019). "ENMD-2076 is more selective for Aur A than Aurora kinase B (IC50, 14 nM and 350 nM, respectively); however, inhibition of both is likely in tumor tissue, based on the drug exposure observed in this study." (PMID 30071865, 2018). "Key mitotic regulators, including kinases such as PLK1, AURKA, AURKB, and MPS1 and kinesins such as CENPE and Eg5, are frequently overexpressed in NSCLC and SCLC, contributing to chromosomal instability, aneuploidy, and highly proliferative tumor phenotypes." (PMID 42076055, 2026). "Tumor from the K215R group were significantly smaller, confirming a diminished tumorigenic capacity in the absent of AURKB acetylation." (PMID 40710353, 2025). "By sequestering microRNAs that would otherwise target and repress AURKB mRNA, MTND4P12 may facilitate the aberrant expression of this kinase, leading to tumor growth and metastasis." (PMID 40781241, 2025). "AURKB, as a downstream key node of the FTO/SP1/AURKB pathway, could influence the tumor microenvironment of GC." (PMID 38956367, 2024). "Aurora B kinase (AURKB) inhibitors have been trialled in a range of different tumour types but are not approved for any indication." (PMID 39521795, 2024). "Furthermore, it was showed that the inhibitor specific for AURKB (AZD1152) can suppress CCNE1 expression in CRC cells and inhibit tumor cell growth." (PMID 38713155, 2024). "It was hypothesized that AURKB is abundantly expressed in CRC cells and tissues, which accelerated the cell cycle progression of tumor cells through its regulation on the expression of key cycle regulators." (PMID 38713155, 2024).
tumor (continued). "After the detection of hub genes utilizing the PPI network of common upregulated genes, the top five hub genes, including AURKA, AURKB, KIF20A, MELK, and TTK that played the most critical role in both primary tumor cell and P7731 cell line, were selected to validate the study." (PMID 37231064, 2023). "Upregulation of alternative kinases including aurora kinase B (AURKB), effect of tumor microenvironment on FLT3 clone sensitivity, and metabolic reprogramming have all been implicated as additional mechanisms resulting in early or late resistance to gilteritinib." (PMID 36900407, 2023). "This was explored further in the dose-expansion part of this study in patients with SCLC (to be published separately), which assessed the pharmacodynamic effects of AURKB inhibition to assess AZD2811 target inhibition and its downstream effect in tumour tissue." (PMID 36871042, 2023). "AURKB was selected as an example of this class, and western blots probing AURKB showed that protein rhythmicity was, in fact, evident in tumor but not in healthy liver." (PMID 37714462, 2023). "Finally, we used the ssGSEA method to determine the correlations between ESPL1, AURKB, BUB3, and FAM83D and 24 types of tumor-infiltrating immune cells." (PMID 35646670, 2022). "The expression levels of CCND1, VEGFA, AURKB, HDAC1, HSP90AA1, and HSP90AB1 were positively correlated with immune cell infiltration levels, whereas the expression levels of SIRT2 and CASP9 were negatively correlated with the tumor purity of BRCA." (PMID 35845599, 2022). "The results revealed that the tumor volume of the stable AURKB knockdown group was significantly smaller than that of the PTX-resistant group, and the tumor volume was also significantly lower in the mutant-type AURKB overexpression group than in the wild-type overexpression group." (PMID 35088239, 2022). "AURKB phosphorylation is not necessary during the generation of multinucleated and polyploid tumor cells." (PMID 35088239, 2022). "In samples from patients with 27 out of 33 tumor types, excluding KICH, PAAD, sarcoma (SARC), SKCM, THCA and THYM, AURKB has markedly higher expression in tumor tissues than in normal tissues." (PMID 33451333, 2021). "In addition, the expression of the cell proliferation markers AURKA, AURKB, CCNB1, and MKI67 was higher in the patients’ tumor tissues than those of normal tissues." (PMID 34503223, 2021). "This implies that AURKB disruption leads to a decrease in cell proliferation and cytokinesis whereas disruption in BRCA1/BRCA2 resulted in abnormal cytokinesis, eventually, encouraging tumor progression." (PMID 33915740, 2021). "Our analysis showed that AURKB expression is three times higher in tumour samples from smokers than never smokers." (PMID 32564237, 2020). "In multivariate analysis including the standard covariates; tumor grade, tumor size, nodal status and age, Aurora kinase B was not a significant and independent marker of decreased disease-free or overall survival." (PMID 25885472, 2015). "We hypothesize that miRNAs that show significant up- or downregulation in GPs may regulate the expression of genes that are involved in the cell cycle (AURKB, CDC45, and CDK6), cell proliferation (EGFR and VEGFA), and angiogenesis (VEGFA) that support tumor growth." (PMID 40143207, 2025). "Our patient tumor sequencing data shows the overexpression of AURKA and AURKB (average Z-score = 2.33 and 2.18, respectively); the result that Panobinostat decreases AURKB shows again that it is targeting another pathway which may be playing an important role in tumor progression." (PMID 39518006, 2024). "In addition, the expression of AURKB and Ki-67 was positively correlated in TCGA CRC tumor tissues." (PMID 38713155, 2024). "Furthermore, AURKB expression has been found to correlate significantly with the infiltration of immune cells, the presence of immunomodulatory genes, TMB and MSI within tumours." (PMID 38898693, 2024).
tumor (continued). "The results revealed the high expression of AURKB, CCNA2, and PLK1 in tumor tissues when compared to normal tissues and we also found that there was a strong positive correlation with the DNA replication, G2M checkpoint, and tumor proliferation signature pathways." (PMID 37238607, 2023). "Indeed, several chemotherapeutic drugs and radiation are known to be able to induce senescence in tumor cells, including inhibitors of CDK4, aurora kinase B (AURKB), casein kinase 2 (CK2), and sunitinib, a known multi-targeted receptor tyrosine kinase inhibitor." (PMID 30687637, 2018). "A new study demonstrated that AZD2811, an AURKB inhibitor, can be formulated in a nanoparticle named accurin to attenuate the side effect and increase the efficacy of AZD2811 in mouse tumor xenograft models, which may give a new direction for the development of AKIs." (PMID 28147341, 2017). "However, we did not identify a significant level of endoreduplication downstream of AKI except at relatively high doses in vitro and within our treated tumours in vivo, which may reflect concomitant inhibition of AURKA and AURKB at these dosages." (PMID 23328114, 2013). "Moreover, activation experiment of SC-79 in vivo revealed that SC-79 promoted the tumor growth and lung metastasis of HCCC9810- AURKB-KD mice, whereas inhibition experiment of MK-2206 in vivo showed that MK-2206 inhibited the tumor growth and lung metastasis of RBE AURKB-OE mice." (PMID 37318676, 2023). "Therefore, proof of principle in terms of sufficient Aurora kinase B inhibition leading to corresponding tumor shrinkage could not be proved in this trial." (PMID 25529193, 2015). "One might speculate that LXY18 disables an upstream regulator that specifies AURKB localization and its disruption by LXY18 led to a persistent activation of the spindle assembly checkpoint response in tumor cells, but not in non-transformed cells." (PMID 37903144, 2023).
infection (11 papers, 2010 to 2023). The state of being infected such as from the introduction of a foreign agent such as serum, vaccine, antigenic substance or organism. "The results show a significant decrease in AURKB mRNA levels at late-times post-infection, and the decrease was enhanced with high fitness HCV p200." (PMID 36992689, 2023). "After depletion of INCENP, ANAPC, and AURKB, the time window was extended 3–5 fold resulting in a doubling or more in infection." (PMID 24874089, 2014). "Infection of renal progenitors with NICDs consistently resulted in the upregulation of transcription of Aurora kinase B (p < .05 vs. mock), as well as in a downregulation of p27Kip1 (p < .05 vs. mock)." (PMID 20680961, 2010). "Thus, under these co-culture conditions both infection transmission and cytosolic mixing were significant, and the extent of both was stimulated by inhibiting AURKB." (PMID 37459363, 2023). "To test whether prolongation of mitoses enhanced the probability of nuclear import (and infection), we depleted cells of mitotic regulators from the screen such as AURKB, INCENP, and ANAPC by RNAi to induce prolonged mitosis." (PMID 24874089, 2014). "Strikingly, inhibiting the key mitotic regulator Aurora kinase B (AURKB) in HIV-1 infected cells significantly increased HIV activity in cell-to-cell fusion and transmission but had little effect on cell-free infection." (PMID 37459363, 2023). "We show that infection resulted in a HCV fitness-dependent, average decrease of the levels of H3Ser10ph, AURKB, and histone H4 tri-methylated at Lysine 20 (H4K20m3) in the infected cell population." (PMID 36992689, 2023). "Among these factors, the cell cycle regulators aurora kinase B (AURKB) and cyclin-dependent kinase 6 (CDK6) were shown to be resistance factors restricting EV-A71 infection, with the nuclear egress of CDK6 regulated by EV-A71." (PMID 33381104, 2020). "The results show significant reductions of AURKB at late times post-infection, that were more accentuated with HCV p200 than HCV p0; the difference between the two viruses reached 3.3-fold at 144 h post-infection." (PMID 36992689, 2023). "In one recent study, productive HIV-1 cell-free infection of primary T cells was inhibited by a selective AURKA inhibitor but not by a selective AURKB inhibitor, barasertib." (PMID 37459363, 2023).
hematological malignancies (7 papers, 2020 to 2025). "AURKA and AURKB were downregulated upon curcumin treatment and both promote tumorigenesis in both solid and hematological malignancies." (PMID 34981672, 2022). "Aurora kinases (AURKA and AURKB) are mitotic kinases with an important role in the regulation of several mitotic events, and in hematological malignancies, AURKA and AURKB hyperexpression are found in patients with cytogenetic abnormalities presenting a unfavorable prognosis." (PMID 33277547, 2020). "In hematological malignancies, AURKA and AURKB overexpression are found in patients with cytogenetic abnormalities that are unfavorable to the prognosis and which compromise patients' survival." (PMID 33277547, 2020).
adenocarcinoma (2 papers, 2022 to 2023). A common cancer characterized by the presence of malignant glandular cells. "AURKB has been suggested to relate to androgen signaling in transgenic adenocarcinoma of the mouse prostate." (PMID 34593983, 2023). "The expression of AURKA and AURKB was higher in CRPC of neuroendocrine type than in CRPC adenocarcinoma, consistent with the poor prognosis for patients with CRPC of neuroendocrine type." (PMID 35853811, 2022). "Moreover, the expression of AURKA and AURKB was higher in CRPC of the neuroendocrine type than in CRPC adenocarcinoma, consistent with the poor prognosis for patients with CRPC of the neuroendocrine type." (PMID 35853811, 2022).
gastrointestinal tumors (1 paper, 2021). "PBK, AURKB, KIF11, and PLK1 confirmed that they are closely related to the occurrence and progression of gastrointestinal tumors, including HCC." (PMID 34200261, 2021).
AURKB also shares sentences with these, for which no sentence is quoted: endometrial cancer (10 papers); acute lymphoblastic leukemia (5); oral cancer (5); viral infection (5); colorectal adenocarcinoma (3); B-cell acute lymphoblastic leukemia (2); brain tumor (2); cervical squamous cell carcinoma (2); depression (2); diabetes (2); esophageal squamous cell carcinoma (2); gastric tumor (2); laryngeal carcinoma (2); liposarcoma (2); metastatic colorectal cancer (2); metastatic prostate carcinoma (2); multiple myeloma (2); prostate adenocarcinoma (2); thyroid follicular carcinoma (2); uveal melanoma (2); acute leukemia (1); acute myocardial infarction (1); acute promyelocytic leukemia (1); African sleeping sickness (1); age (1); allergic asthma (1); Alzheimer disease (1); aneuploidy (1); Anxiety (1); astrocytic tumor (1).
A further 65 diseases each share a sentence with AURKB in 1 paper.